PGAM1 (phosphoglycerate mutase 1)
Diseases named in the same sentence as PGAM1 in open-access papers (continued):
Sharing a sentence is not in itself a finding about the gene and the disease.
tumor (continued). "Furthermore, analysis of immunohistochemical staining data from the Human Protein Atlas verified that the PGAM1 protein was upregulated in KIRC tumor tissues relative to normal tissues." (PMID 37847178, 2023). "Our study demonstrates that increased PGAM1 expression is linked to poor prognosis in KIRC and may impact the tumor microenvironment and macrophage infiltration." (PMID 37847178, 2023). "The PGAM1 expression level of tumor tissue and adjacent normal tissue was assessed." (PMID 37705495, 2023). "Moreover, metabolite levels showed that silencing PGAM1 markedly suppressed the RFX6‐induced glycolysis in vivo, presenting as attenuated lactate and 2‐PG production in the subcutaneous tumours from the stable PGAM1‐KD groups." (PMID 38093528, 2023). "While the extracellular tumor-linked roles of PGAM1, LDHA, PKM, TPI1, and PGK1 have not been tested, the anti-tumor actions of ALDOA 13, 18, ENO1 16, 18, and GAPDH 20 were reported." (PMID 37056934, 2023). "Given our previous findings of PGAM1 overexpression in renal injury models and human KIRC, and the crucial role of the tumor immune microenvironment (TIME) in tumor growth, metastasis, and immune evasion, we further analyzed the relationship between PGAM1 and tumor-immune interactions." (PMID 37847178, 2023). "Therefore, PGAM1 has been potentially targeted as a promising therapeutic candidate for tumor therapy." (PMID 36077431, 2022). "Our results demonstrate a better understanding of PGAM1‐mediated molecular network in tumor formation, and therefore, this cascade might be targeted for BC therapy." (PMID 35674458, 2022). "Here, we revealed that silencing of PGAM1 could reconstruct the expression of ASS1 in BC cells to exert tumor‐suppressive effects." (PMID 35674458, 2022). "High expression of PGAM1 is closely correlated with lymphatic metastasis and tumor re-occurrence, which might account for the poor prognosis." (PMID 35610567, 2022). "Next, we analyzed tumor tissue samples from 83 BC patients to further assess the effects of PGAM1." (PMID 35674458, 2022). "We found that PGAM1 was upregulated in tumor samples compared to the control group." (PMID 35674458, 2022). "Inactivation of PGAM1 gene increases apoptosis rates and decreases tumor proliferation and growth." (PMID 33668689, 2021). "The sixth enzyme that displayed downregulated expression (1.6 fold decrease) in KO tumor is Pgam1." (PMID 34685767, 2021). "PGAM1 silencing inhibits mTOR‐dependent glycolysis, cell proliferation, and tumor formation." (PMID 32167655, 2020). "Finally, in vivo experiments further validated that miR-3614-5p inhibited NSCLC tumor growth by targeting PGAM1." (PMID 32855383, 2020). "In addition, circ‐PGAM1 silencing combined with miR‐542‐3p overexpression yielded the maximum tumor‐suppression effect." (PMID 32167655, 2020). "circ‐PGAM1 silencing combined with miR‐542‐3p overexpression significantly inhibited cell proliferation, migration, and invasion and promoted cell apoptosis, whereas miR‐542‐3p silencing offset the tumor‐suppression function of simple circ‐PAGM1 silencing." (PMID 32167655, 2020). "The tumor volume was lowest in circ‐PGAM1(−) + pre‐miR‐542‐3p group." (PMID 32167655, 2020). "Previously we found that PGAM1 could balance the intracellular concentrations of its substrate 3PG and its product 2PG to control tumor growth." (PMID 30818883, 2019). "In addition, both downregulation of PGAM1′s expression and inhibition of its metabolic activity has been shown to attenuate cell proliferation and tumor growth." (PMID 29890679, 2018). "As PGAM1 is critical for tumor growth and is abundant in cells with hyperactive mTOR unveiled in this study, we checked whether the enhanced PGAM1 expression was essential for RTK-PI3K-AKT-mTOR-mediated aerobic glycolysis and oncogenesis." (PMID 29362480, 2018). "Furthermore, reduction of PGAM1 in these cells suppressed cell proliferation in vitro and blunted tumor formation of these cells in nude mice." (PMID 29362480, 2018).
tumor (continued). "Interestingly, PGAM1 that has been shown upregulated in ccRCC tumours was found to downregulated in response to PHD3 depletion." (PMID 28680592, 2017). "Moreover, both SEC61G and PGAM1 may contribute to microglial polarization (M1/M2 states), remodeling the brain metastatic niche and facilitating immune evasion and tumor progression." (PMID 39990664, 2025). "In addition, the overexpression of PGAM1 protein in UVM patient tumor tissues was also confirmed by us by immunohistochemistry, suggesting that PGAM1 might be used for the clinical detection and prognosis evaluation of UVM." (PMID 38434965, 2024). "Therefore, PGAM1 may be directly involved in inhibiting tumor immune clearance by up-regulating PD-L1." (PMID 38434965, 2024). "Moreover, we found that PGAM1 expression was correlated with TMB and MSI in more than 10 types of tumors, and these two factors have been reported to be important biomarkers for predicting ICI efficacy and prognosis 58, 59, which further supports the potential link between PGAM1 and tumor immunity." (PMID 38434965, 2024). "In addition, inhibiting PGAM1 protein can inhibit tumor growth." (PMID 34435138, 2021). "In the present study we identified four candidate tumor-associated antigens, including chaperonin containing TCP1 subunit 5 (CCT5), heat shock 70 kDa protein 8 isoform 1 (HSP70), eukaryotic translation elongation factor 1 gamma (eEF1), and phosphoglycerate mutase 1 (PGM1)." (PMID 28969060, 2017). "Interestingly, pathway analysis revealed that tumours 1203/1204 demonstrated significant enrichment for the term glycolysis/gluconeogenesis, reflecting increased tyrosine phosphorylation of several metabolic enzymes, including Pgam1, Pkm2 and Pgk1." (PMID 25200860, 2014). "(J) Analysis of a published scRNA-seq dataset of tumor-infiltrating Tregs (TIL-Tregs) shows that PGAM1 is overexpressed in the most highly suppressive subpopulation, out of proportion to proximal rate-limiting glycolytic enzymes." (PMID 40720256, 2025). "PFKP, PGAM1 and PGK1 are key metabolic enzymes in lung cancer, contributing to tumour progression and patient prognosis." (PMID 41154605, 2025). "Seven GRPGs (PIM2, PGK1, ADPGK, YWHAZ, PTK2, PGAM1, and VDAC1) were significantly upregulated in the TCGA-BRCA tumor tissues." (PMID 40046063, 2025). "For example, an allosteric inhibitor (KH3) of phosphoglycerate mutase 1 (PGAM1) promotes HCC ferroptosis, increases the number of tumor-infiltrating CD8+ T cells, and enhances the efficacy of anti-PD-1 immunotherapy in HCC." (PMID 39614322, 2024). "Collectively, data suggest that PGAM1 Y119 phosphorylation is required for PKM2 recognition, and beneficial for tumor cells." (PMID 38750259, 2024). "A PGAM1-derived pY119-containing peptide has been synthesized, which indeed interfers with the interaction of PGAM1 and PKM2, and significantly inhibits tumor growth in mice." (PMID 38750259, 2024). "In response to epidermal growth factor signaling, Src-catalyzed PGAM1 Y119 phosphorylation is a prerequisite for PKM2 binding and the subsequent PGAM1 H11 phosphorylation, which constitutes a discrepancy between tumor and normal cells." (PMID 38750259, 2024). "The results revealed a significant increase in PGAM1 and CD31 (vascular endothelial cell marker) expression in tumor tissues of patients with PCa compared to adjacent tissues." (PMID 37542027, 2023). "Our results confirmed that PGAM1 silencing inhibited the proliferation of HCC cells in vitro and tumor growth in vivo in a ferroptosis‐dependent manner and potentiated the infiltration of CD8+ T‐cells." (PMID 37705495, 2023). "Findings were validated with tumor specimens from 60 KIRC patients, correlating PGAM1 expression with clinicopathological features and prognosis using bioinformatics and immunohistochemistry." (PMID 37847178, 2023).
tumor (continued). "To further verify that this synergistic effect was dependent on CD8+ T‐cells mediated by PGAM1 inhibition, we depleted CD8+ T‐cells in a subcutaneous tumor model in C57BL/6 mice." (PMID 37705495, 2023). "The next PGAM1 inhibitor is KH3, which has shown anti-tumor activity in vitro and in vivo in pancreatic ductal adenocarcinoma." (PMID 35628385, 2022). "Western blotting was used to assess the levels of ENO1, c-Myc, β-catenin, MMP-9, PGAM1, and MMP-13 in SKCM-derived cell lines or tumor tissues from patients with SKCM." (PMID 35925486, 2022). "PGAM1 knockdown increases 3-PG accumulation in serine-starved PDAC cells, resulting in increased cell proliferation and tumor formation." (PMID 36339551, 2022). "For instance, prominent glycolytic enzymes, such as LDHA and phosphoglycerate mutase 1 (PGAM1), have been shown to promote tumor cell proliferation." (PMID 34367973, 2021). "Enzymatically independent activities of enzymes, such as PGAM-1 and LSD1, provide potential targets for clinical tumor therapy." (PMID 32312975, 2020). "Among malignant CMTs, autoantibodies to TPI, MUC1, PGAM1, CMYC and MNSOD, were present across all tumour grades." (PMID 30361548, 2018). "PGMI-004A, a small molecular inhibitor of PGAM1, was found to decrease glycolysis, PPP flux, and biosynthesis, and consequently block cell proliferation and tumor growth." (PMID 29362480, 2018). "Glycolytic targets of tyrosine kinase signaling include PGAM1, PKM2, and LDHA where phosphorylation of each of these enzymes promotes increased glycolytic rate and increased tumor cell proliferation." (PMID 30087897, 2018). "In line with these insights, depletion of PGAM1 in NCI-H1299 and MDA-MB-231 cells only partially rescue the anti-tumor effects of EGCG." (PMID 28611670, 2017). "So, future works will determine if there is a direct relation between altered proteins, such as PGAM1 and ADK, related with rapid growth of tumour cells and an increased weight of vitrified pups." (PMID 25915775, 2015). "Immunohistochemical analysis was performed to characterize the distribution of PGAM-1, HSPD1, PDIA3 and SSP411 in surgical tumor tissues." (PMID 23118872, 2012). "Western blotting was used to quantify the expression of PGAM-1, HSPD1, PDIA3 and SSP411 (which were all upregulated in bile from CC patients) in eight pairs of CC and adjacent non-tumor bile duct tissues." (PMID 23118872, 2012). "Simultaneously, the immune-cells around the tumor tissue also showed high immune-intensity for HSPD1 and PGAM-1." (PMID 23118872, 2012). "In the tumor microenvironment, where serine availability is limited, PKM2 coordinates with the c-Myc-responsive long non-coding RNA gLINC to assemble a metabolic enzyme complex comprising PGK1, PGAM1, ENO1, and LDHA." (PMID 40842995, 2025). "In addition, GSE29044 had more differentially expressed GRPGs between normal and tumor tissues (CS, PGK1, HNRNPA1, ADPGK, YWHAZ, PTK2, and PGAM1) than GSE42568 (CS, HNRNPA1, ADPGK, and PTK2)." (PMID 40046063, 2025). "Together, SEC61G may regulate PGAM1 stability and activity by modulating UBE3C-mediated ubiquitination, providing new insights into the role of SEC61G in tumor metabolic reprogramming." (PMID 39990664, 2025). "Non-canonical PKM2 function controls PGAM1 and macromolecule biosynthesis during metabolic reprogramming and tumor growth." (PMID 38750259, 2024). "Our work not only supports the conclusion that PEP-dependent PGAM1 H11 phosphorylation occurs in PKM2-expressing tumor cells but also provides a more detailed molecular mechanism for PEP-based phosphotransferring to PGAM1 when pyruvate kinase activity of PKM2 is reduced." (PMID 38750259, 2024). "Therefore, it can be inferred that the succinyltransferase function of HAT1, coupled with the succ of PGAM1 mediated by HAT1, stands as a critical mechanism driving tumor progression." (PMID 39278916, 2024).
tumor (continued). "In addition, we analyzed the intrinsic connection between PGAM1 and MSI/TMB, two predictive markers for tumor immunotherapy." (PMID 38434965, 2024). "In the absence of HAT1, PGAM1 succinylation and its activity were reduced in tumour cells and re-expression of a mutant that was not permissive to lysine succinylation (PGAM1-K99R) in PGAM1-KO cells, therefore showed reduced tumour cell proliferation." (PMID 38213532, 2023). "To validate whether PGAM1‐mediated CD8+ T‐cell infiltration is ferroptosis dependent, we detected HCC tumor growth in vivo in the absence or presence of liproxstatin‐1." (PMID 37705495, 2023). "In vitro cell experiments have shown that interfering with DARS2 expression can inhibit the proliferation and migration of LUAD cells, promote cell apoptosis, and inhibit the glycolytic activity of tumor cells by inhibiting the expression of glycolytic related genes SLC2A1, GPI, ALDOA, and PGAM1." (PMID 37626419, 2023). "Compared with responders who achieved a partial response after the administration of anti‐PD‐1 immunotherapy, nonresponders who demonstrated an enlargement of tumor size had higher PGAM1 and LCN2 expression as well as lower CD8 expression." (PMID 37705495, 2023). "PGAM1 regulates Hypoxia-inducible factor 1α (HIF-1α) and PI3K/Akt/mTOR pathways that in turn can provide required energy for proliferation, invasion, and metastasis of tumor cells." (PMID 37501157, 2023). "Univariate Cox regression analysis showed that ALT, GGT, AFP, tumor size, tumor encapsulation, macroscopic tumor thrombus, microvascular invasion (MVI), lymphatic metastasis, differentiation grade, BCLC stage and PGAM1 expression were significantly correlated with the survival of HCC patients." (PMID 37705495, 2023). "Our study indicated for the first time that knockdown of PGAM1 could reconstruct the expression of ASS1 in BC cells, resulting in a decrease in tumor growth and exerting antitumor effects via cAMP/AMPK/CEBPB axis." (PMID 35674458, 2022). "Moreover, we assessed the expression of PGAM1 and ASS1 in tumor tissues of these four groups collected at the end of the experiment by IHC." (PMID 35674458, 2022). "In addition, we found that there was a significant positive correlation between the PGAM1 and advanced TNM stage and tumor proliferation marker (Ki-67 and PCNA) expression levels." (PMID 32855383, 2020). "Interestingly another novel PGAM1 allosteric inhibitor, HKB99, has been reported to suppress tumor growth and metastasis and overcome drug resistance in NSCLC12." (PMID 32855383, 2020). "When PGAM1 is inhibited by a small molecule or shRNA, intracellular level of 3PG increased and 2PG decreased which led to the blockade of PPP, serine synthesis, glycolysis and subsequently impaired tumor growth." (PMID 30818883, 2019). "Therefore, PGAM1 may be a key immune modulator in TME, widely involved in regulating tumor immune status." (PMID 38434965, 2024). "Additionally, targeting phosphoglycerate mutase 1 (PGAM1) has shown promise in promoting ferroptosis and enhancing CD8 + T cell infiltration, which, when combined with ICIs, could amplify anti-tumor effects." (PMID 39117626, 2024). "Interestingly another novel PGAM1 allosteric inhibitor, HKB99, has been reported to could suppress tumor growth and metastasis and overcome drug resistance in NSCLC26." (PMID 32855383, 2020). "Besides, PGAM1 has no obvious correlation with the clinical pathological characteristics of patients including age; lymph node (LN) metastasis; tumor‐necrosis‐metastasis (TNM) stage; and estrogen receptor (ER), progesterone receptor (PR), and human epidermal growth factor receptor 2 (HER2) statuses." (PMID 35674458, 2022). "Ubiquitously expressed proteins like PGAM1 and syntenin may not represent promising markers: the release of such proteins by many cell types in the body including hematopoetic cells would presumably confound sensitive detection of a tumor-specific release." (PMID 20184735, 2010).
tumor (continued). "PGAM-1, HSPD1, PDIA3 and SSP411 were overexpressed in tumor tissues compared to the matched non-tumor tissues." (PMID 23118872, 2012).
infection (4 papers, 2020 to 2025). The state of being infected such as from the introduction of a foreign agent such as serum, vaccine, antigenic substance or organism. "The relative mRNA expression levels of Mx1 and TOP1 were significantly upregulated, whereas those of eIF4E, G6PD and PGAM1 were significantly downregulated in PK-15 cells during infection with SVA." (PMID 35632606, 2022). "Furthermore, Pgam1 KO mice showed a lower expansion of OVA-specific CD8 T cells in the spleen after OVA-peptide-expressing Listeria monocytogenes (Lm-OVA) infection." (PMID 32709928, 2020).
neurological disease (2 papers, 2020 to 2024). "In this manner, the elevated PGAM1 saliva levels could be of particular interest, as FMS has been associated with several neurological disorders." (PMID 38652420, 2024).
adenocarcinoma (1 paper, 2015). A common cancer characterized by the presence of malignant glandular cells. "Our data of PGAM1 over-expression agrees with that previously found in SCLC and adenocarcinomas (AC)." (PMID 26104294, 2015).
PGAM1 also shares sentences with these, for which no sentence is quoted: oral squamous cell carcinoma (5 papers); renal clear cell carcinoma (4); psychiatric disorder (3); lung squamous cell carcinoma (2); neuromyelitis optica (2); Obesity (2); urothelial bladder cancer (2); asthma (1); autoimmune hepatitis (1); Autoimmunity (1); cervical cancer (1); cholangitis (1); chromophobe renal cell carcinoma (1); depression (1); Hyperglycemia (1); intrahepatic cholangiocarcinoma (1); kidney cancer (1); liver disease (1); lymphoma (1); Menkes disease (1); mental disorder (1); papillary renal cell carcinoma (1); Sepsis (1); skin melanoma (1); small cell lung carcinoma (1).